SMAD4 (SMAD family member 4)
Diseases named in the same sentence as SMAD4 in open-access papers (continued):
Sharing a sentence is not in itself a finding about the gene and the disease.
tumor (continued). "TGFβ has a dual nature: the tumor-intrinsic TGF-β plays a tumor suppressive function in the early stages through SMAD4-regulated genes, but the stromal-derived TGF-β promotes cancer growth and immunosuppressive mechanisms in the later stages, upon SMAD4 inactivation." (PMID 39195299, 2024). "Hence, measuring the levels of TAp73, SMAD4 and/or pERK could help to predict whether TGF-β preferentially uses an oncogenic or a tumor-suppressive pathway in a given patient and at a specific time." (PMID 37568607, 2023). "Because TGF-β signaling activation leads to the accumulation of Prdm16 through the suppression of Smad4 inhibitory effects, one would speculate that Smad4 and Prdm16 might function in the same signaling network that integrates the TGF-β tumor promoter effects during PDAC progression." (PMID 36828547, 2023). "Tumor cellular assays, qRT-PCR, western blot, ChIP, luciferase assays and CRISPR-Cas9 editing methods were performed to mechanistically understand the cooperation of GATA2 with SMAD4 in promoting TGFβ1 and AR signaling and mediating inherited PCa risk and progression." (PMID 37550764, 2023). "Interestingly, preserved SMAD4 or RUNX3 resulted in similar 5-year DSSs in the tumor epithelial compartment ( 70%), but not in the stromal compartment (SMAD4-/RUNX3+ 80%, SMAD4+/RUNX3- 60%)." (PMID 36900240, 2023). "However, subsequent studies have shown that Smad4 inactivation in the context of KrasG12D (KSC) led to the acceleration of PDAC, unequivocally confirming the tumor suppressor role of TGF-β signaling in PDAC." (PMID 36828547, 2023). "While all tumor cell lines had increased PD-L1 expression compared to non-malignant HPNE cells, PD-L1 expression was highest in BxPC-3 cells with homozygous deletion of SMAD4 and AsPC-1 cells harboring an inactivating SMAD4 mutation." (PMID 35155243, 2022). "Thus, SMAD4 mutation and/or loss in EAC seems to be the switch that changes BMP signaling from tumor-suppressive canonical BMP signaling, to tumor-promoting non-canonical BMP signaling." (PMID 35902550, 2022). "Secondly, re‐expression of Smad4 failed to completely reverse Smad4KO‐induced tumor inhibition, and this may be attributed to persistent DNA damage and STING upregulation." (PMID 35064757, 2022). "The results obtained for transcript SMAD4–201 in human tumor and non-tumor tissue samples may indicate the translational potential of this molecule as a putative CRC biomarker." (PMID 35034624, 2022). "Notably, PZH has exhibited therapeutic efficacy against tumor metastasis and EMT by targeting the TGF-β/Smads signaling pathway, resulting in a decrease in N-cadherin, TGF-β, p-Smad2/3, and Smad4 expressions, while an increase in E-cadherin expression in vitro and in vivo." (PMID 35308223, 2022). "Finally, Smad4KO‐mediated tumor growth inhibition was significantly, but not completely, reversed after Smad4 re‐expression." (PMID 35064757, 2022). "SMAD4 was observed in all cells irrespective of how the tumor sample was processed." (PMID 36582292, 2022). "To determine whether the observed SMAD4-dependent alterations in cytokine and chemokine production correspond to changes in T-cell activation, we again utilized PANC-1 tumor cells, which were incubated with either a control siRNA (siControl) or siRNA against SMAD4 (siSMAD4)." (PMID 35155243, 2022).
tumor (continued). "Moreover, 82.52% (104 cases) of tumours with positive TGF-β signalling showed a high expression of Smad4 in the nucleus and 17.48 % (18 cases) of tumours indicated low expression of Smad4 with negative TGF-β signalling." (PMID 35456495, 2022). "SMAD4 degradative defects in HPV-positive cell lines might be also explained by the fact that HPV downregulates βTRCP1 expression, leading to a lower expression of this ligase in HPV-positive HNC cell lines and tumours compared to HPV-negative." (PMID 35144669, 2022). "Unlike Smad2 and Smad4, Smad3 nuclear localization is diminished in tumor samples." (PMID 34501347, 2021). "PDAC cells lacking expression of the tumor suppressor SMAD4 were shown to release sEVs containing miR-1260a and miR-494-3p, which changed the balance between DCs and MDSCs towards a higher number of M- and G-MDSCs, thereby promoting proliferation, glycolysis, and immunosuppression." (PMID 34638330, 2021). "Our Smad4-mutant tumor model lacks PD-L1 expression in vitro, and although the in vivo tumors were PD-L1-positive, the PD-L1 expression was primarily on infiltrating immune cells rather than on the tumor cells themselves." (PMID 34433873, 2021). "For example, endogenous TGFβ signaling is considered oncogenic in tumor cells lacking SMAD4." (PMID 34680235, 2021). "However, a dual function of SMAD4 during the course of HCC onset and progression, where it may exert a tumor-suppressive function at an early stage and an oncogenic function at later stages, should be taken into consideration." (PMID 34571856, 2021). "Moreover, we found that FAK KD HepG2 and Huh-7 cells, but not macroH2A1 KD HepG2 and Huh-7 cells, displayed a simultaneous significant increase (p < 0.01) in the mRNA levels of cancer stemness suppressor genes GATA6, SMAD4, and BMP7, and of tumor-promoting genes KDR and SOX2." (PMID 33182805, 2020). "Consequently, TrkB could inhibit the TGF-β-mediated tumor suppressor activity through direct interactions with SMAD2, SMAD3, or SMAD4, as exemplified by c-Myc and Tax." (PMID 32340410, 2020). "S100A8/9 boosted migration and proliferation in cells with or without Smad4 tumor cells." (PMID 33117687, 2020). "But, tumor cells with transient decrease of Smad4 do not react to S100A8, but not S100A9." (PMID 33117687, 2020). "We can suppose that the balance between the positive and negative role of SMAD4 towards NK cell anti-tumor functions may be due to the different TGF-β content of tumor microenvironments or to distinct stages of cancer progression." (PMID 31948072, 2020). "Among the tumor-related genes, the top amplified genes included ERBB2 (17q21), MYC (8q24), GNAS (20q13), EGFR (7p11), ZNF217 (20q13), CCNE1(19q12), NCOA3 (20q13), and CDK6 (7q21), and the most frequently deleted genes were CDKN2A (9p21), CDKN2B (9p21), KIT (4q12), SMAD4 (18q21), and FGFR1 (8p12)." (PMID 31541076, 2019). "SMAD4 deficiency also accelerated PDAC development in KrasG12D combined with INK4A/ARF heterozygous-loss mice and affected the histological type of PDAC with a more highly differentiated type, rather than a poor differentiate tumor." (PMID 31480737, 2019). "Among the 23 EGFR-mutated patients treated with erlotinib, 17 (74%) responded, 4 (17%) had no OR, and 2 (9%) harboring a SMAD4-mutation (p.R135*(stop)) and a FGFR3-mutation (p.D785fs*31), respectively, showed mixed response with simultaneously progressing and responding tumor lesions." (PMID 29899852, 2018). "Smad4 expression showed a negative correlation with tumor size." (PMID 29103082, 2018). "Moreover, we observed that the number of S100A8-positive monocytes was significantly lower in tumours which lacked Smad-4, suggesting a paracrine interaction between tumour cells and the monocytic stromal compartment." (PMID 30558665, 2018).
tumor (continued). "Although the immunosuppressive activities of TGFβ1 in the tumor microenvironment have been accepted as one rational explanation, this does not explain the role that TGFβ1 plays within tumor cells lacking functional Smad4 to promote proliferation, metastasis, and apoptotic resistance." (PMID 28649369, 2017). "It is shown in the mouse pancreatic model that tumor suppressive effects of Tif1γ could be independent of Smad4." (PMID 28067794, 2017). "However, deletion of a number of key TGFβ signaling components (e.g., TGFβ1, TGFBR1, SMAD2/3, and SMAD4) alone in the ovary does not induce tumor formation, challenging TGFβ signaling as essential tumor suppressor in the ovary." (PMID 27344183, 2016). "Over-expression of Smad4 rescued the NB cells from LEF1-facilitated growth, invasion and angiogenesis, suggesting that Smad4 may exert its tumor suppressive functions, at least in part, through interacting and repressing the LEF1 activity in regulation of HPSE expression in NB." (PMID 27595937, 2016). "However, SMAD4 and CD44 expression was occasionally completely lost in the invasive tumor." (PMID 26098881, 2015). "In addition, our in vivo study using subcutaneous xenografts in SCID mice revealed that SMAD4 re-expression in AsPC-1 cells or its knockdown in PANC-1 does not significantly affect tumor growth in vivo." (PMID 24625091, 2014). "The functional antagonism between COUP-TFII and Smad4 is further evidenced by GEM, in which conditional ablation of Smad4 rescues the invasive tumor growth in mice lacking COUP-TFII, and overexpression of COUP-TFII does not exacerbate tumor malignance further in the absence of Smad4." (PMID 25328664, 2014). "Upon SMAD4 inactivation or deletion, TGF-β1 may preferentially signal through a SMAD-independent pathway, instead of the canonical SMAD-dependent pathway, leading to the phenotypic changes seen in tumor cells." (PMID 24625091, 2014). "The clinical relevance of our experimental observations was supported by a statistically significant inverse correlation between miR-224 and SMAD4 transcript expression in tumor versus paired adjacent non-tumorous tissues from HCC patients (p<0.001, r = −0.45, R2 = 0.122)." (PMID 23922662, 2013). "For other tumor suppressor genes such as MAP2K4, MADH4 (SMAD4/DAC4), ACVR1B (ALK4, activin receptor type 1B) known to undergo germ-line or somatic genetic inactivation in clinically sporadic PC, no germ-line mutations could be identified in any of the FPC kindreds tested." (PMID 24303367, 2013). "However, A good number (12/25, 48%) of tumor tissues showed moderate levels of Smad6 protein expression, in contrast to Smad4 where most of the cases were weakly positive or absent." (PMID 22195733, 2011). "Therefore, by down-regulating the expression of these tumor suppressor genes including Smad4, CD82 and PTEN through cellular miRNAs, a persistent HCV infection could eventually lead to tumor development and metastasis in liver." (PMID 19671175, 2009). "Although the existence of additional unknown target tumour-suppressor genes in the region of 18q21 cannot be ruled out, recently published results strongly suggest a significant contribution of Smad4 gene inactivation in advanced tumour stages." (PMID 12569386, 2003). "Thus BMP4 is required for suppression of metastasis regardless of tumor SMAD4 status." (PMID 38689334, 2024). "Similarly, this study reveals Smad4KO BRAFV600E/+ β-cateningof organoids have the same invasive behaviors seen in Smad4KO BRAFV600E/+ tumor organoids, whereas BRAFV600E/+ β-cateningof organoids did not, suggesting that the loss of SMAD4 was critical for the invasive behavior." (PMID 38136364, 2023).
tumor (continued). "Although B2M, MAPK1, and SMAD4, which are also driver genes, could not be pooled in the meta-analysis, they correlated with neoplasm histologic grade, pathologic stage and N status, final vital status, and HPV status in OSCC as demonstrated by TCGA clinical and pathological correlation analysis." (PMID 36923449, 2023). "IHC staining demonstrated that the Smad4 mRNA nano-lantern successfully restored the Smad4 protein expression in tumor tissues, which intuitively suggested the successful translation of nano-lantern in tumor tissues while the bare mRNA could not." (PMID 36894556, 2023). "Finally, analyses of human tumor transcriptomes showed that SMAD4 mutations are not underrepresented in mesenchymal tumor samples and that expression patterns of EMT-associated genes are similar in SMAD4mut and SMAD4 wild-type (SMAD4wt) cases." (PMID 34857888, 2022). "In in vivo experiments, birabresib significantly reduced the tumor volume of HCT116 SMAD4−/− xenografts, while it did not affect the growth of HCT116 SMAD4+/+ xenografts, further supporting the synthetic lethal interaction between BET inhibition and SMAD4 loss." (PMID 34065438, 2021). "The mutation in Smad4 (a molecule involved in the intracellular signaling pathway of TGF-β) has been proposed as a hypothesis in this regard; the absence of which has caused aggressive tumor behavior in response to TGF-β." (PMID 34094025, 2021). "In addition, some studies have shown that its tumor suppressor function may not be related to SMAD4." (PMID 32908919, 2020). "Moreover, TGF-β could increase the cancer stem cell (CSC) population in a Smad4-dependent manner from clinical and preclinical data, and TGF-β signaling enhances tumor recurrence through interleukin (IL)−8-dependent expansion of CSCs in triple-negative breast cancer." (PMID 29955155, 2018). "Furthermore, in xenografts tumour cells were completely negative by pSTAT3 immunohistochemistry, indicating absence of cytokine/chemokine signalling, but nuclear β-catenin and SMAD4 immunostainings as read-out of wnt and BMP pathway activation, respectively, were maintained." (PMID 29040282, 2017). "We also explored whether PSG9 is a key component in the regulation of TGF-β signaling-induced tumor angiogenesis via enhancement of nuclear retention of SMAD4, and finally, we determined whether the expression of proangiogenic molecules is affected by the PSG9/SMAD4 interaction." (PMID 27528036, 2016). "We did not observe a correlation between the expression of SRC-3, ErbB-2, hTERT, PTEN, FoxO1, Bcl-2, SMAD4, c-myc, Hsp70, Hsp90 and CHIP expression in BxPC-3 cells, this result could be explained by feedback of complicated signaling network in different tumor environments." (PMID 24722501, 2014). "It was observed that selective SMAD4 deletion in the pancreatic epithelium had no discernable impact on pancreatic development or physiology, but when combined with the activated KRASG12D allele, SMAD4 deficiency enabled rapid progression of KRASG12D-initiated neoplasms." (PMID 20565773, 2010). "More particularly, BMP signaling (non-canonical) is triggered by the overexpressed BMP2 and 4, promoting EAC (SMAD4-negative) aggressiveness; however, the inhibition of BMP2/4 via the VHHs limits tumor growth and increases survival." (PMID 41369383, 2025). "The functional relevance of chromosome 18 loss has been discussed longish and controversially with involvement of several tumor suppressors like DCC, Elongin A3, SMAD2, SMAD4, and MIR1-2, but so far, no conclusive results exist." (PMID 40410286, 2025).
tumor (continued). "SMAD4 functions as a key regulator within the TGF-β signaling pathway, and multiple studies have shown that it does not independently initiate tumor formation." (PMID 39459634, 2024). "However, the effect of SMAD4 is not a direct cause of increased tumor invasiveness but rather by affecting multiple aspects of the TGF-β signaling pathway and regulating the expression of downstream target genes, thereby comprehensively influencing tumor behavior." (PMID 39164192, 2024). "Despite increased primary tumor growth, BMP4 suppresses metastasis in the absence of tumor cell expression of SMAD4." (PMID 38689334, 2024). "We observed a downregulation of SMAD4 in tumor tissues relative to paired paraneoplastic samples in 84 PDAC patients, and 2 tumor tissues were not counted due to the absence of paired paraneoplastic samples." (PMID 39528473, 2024). "In the absence of SMAD4, BMP4 promotes primary tumor growth that is accompanied by increased expression of genes associated with DNA replication, cell cycle, and MYC signalling pathways." (PMID 38689334, 2024). "In the presence of SMAD4, enforced expression of BMP4 did not change the rate of tumor growth up to the day of resection." (PMID 38689334, 2024). "In the case of perihilar CCA (pCCA), tumour size, tumour differentiation, STING1 expression, SMAD4 expression, and the co‐absence of STING1 and SMAD4 expression were identified as prognostic factors." (PMID 37488750, 2023). "Other copy number reduced genes included SMAD4, HNF1B, and some gene loci that are not known to be tumor suppressor genes, such as KRAS, MYC, PIK3CA, and IL6." (PMID 36430324, 2022). "Multivariate analysis revealed that nuclear SMAD4 expression was an independent predictor for RFS (HR 0.2, 95% CI 0.04-0.99) besides tumour size (HR 1.1, 95% CI 1.01-1.11), but not for DSS (HR 0.1, 95% CI 0.01-1.64)." (PMID 35756604, 2022). "In summary, the negative expression of SMAD4 was found to be related to malignant phenotypes of PDAC such as lymph node metastasis, tumour size and the degree of differentiation." (PMID 31684910, 2019). "Baseline level of SMAD4 expression was not predictive of PFS, and tumor tissue SMAD4 expression was not available." (PMID 30477242, 2018). "EAC1 and EAC3 showed homogeneous LOH of SMAD4 in all tumor regions, two tumors showed different subclones with LOH or without LOH of SMAD4 (EAC2 and 5), while in EAC4 no LOH of SMAD4 was identified." (PMID 28376920, 2017). "For the tumor suppressors RB1, NF1, and SMAD4, the high-amplitude deletions (<−0.9) are not cleanly separated from the other bins by expression." (PMID 26787600, 2016). "It was found that the mRNA level of Smad4 was not pronouncedly inhibited in human EHCC tissues compared with NBD and adjacent non-tumor tissues." (PMID 26077733, 2015). "Frequent inactivation of the SMAD4 gene appears to be specific to PDAC, as inactivation is rarely noted in other tumor types or in non-ductal neoplasms of the pancreas." (PMID 24624093, 2014). "In their study, they found no Smad4 protein inactivation in stage I patients, 8% in stage II, 6% in stage III and 22% in stage IV patients, indicating that tumour progression correlates with Smad4 protein inactivation." (PMID 17088901, 2006). "Analysis of clinical samples revealed that in SMAD4-negative cancers, the number of neutrophils in the peritumor stroma was markedly higher than in SMAD4-positive cases, and the CXCL8 was strongly expressed by infiltrating neutrophils in the tumor." (PMID 40943634, 2025). "We hypothesized that the activity of SMAD4 mediates the anti-metastatic activity of BMP4, and that when SMAD4 is lost, non-canonical BMP4 signalling promotes tumor growth and metastasis." (PMID 38689334, 2024). "However, in hepatocellular carcinoma, SMAD4, a common SMAD for TGF-β and BMP signaling, has been shown to promote tumor growth via a non-canonical signaling mechanism." (PMID 39404428, 2024).